IL24 (interleukin 24)
Diseases named in the same sentence as IL24 in open-access papers (continued):
Sharing a sentence is not in itself a finding about the gene and the disease.
lung carcinoma (continued). "To determine if the observed IL-24-mediated inhibition on CXCR4 was unique to H1299 cells, we conducted experiments in an additional lung cancer cell line, A549." (PMID 25775124, 2015). "IL-24 binds to dsRNA-activated protein kinase (PKR), leading to apoptosis in lung cancer cells." (PMID 37444474, 2023). "IL-24 can also indirectly inhibit angiogenesis by inhibiting the expression of PI3K/Akt signal, vascular endothelial growth factor VEGF, and transforming growth factor TGF-TGF, which play important roles in angiogenesis of lung cancer cells." (PMID 34685354, 2021). "Overall, investigation of the primary lung cancer tissues over advancing stages of the disease has confirmed the lung cancer cell line studies, supporting the roles of PKR, OAS, and IL-24 as specific lung cancer suppressor candidates, worthy of consideration for therapeutic strategies." (PMID 33562773, 2021). "To determine whether the observed IL-24-mediated downregulation of GLI1 was restricted to one cell line with a stable transfection system, we performed experiments in an additional lung cancer cell line, A549." (PMID 31783569, 2019). "We next investigated whether IL-24 displays its inhibitory effect on GLI1 and its downstream targets in lung cancer cells overexpressing GLI1." (PMID 31783569, 2019). "We observed that IL-24 was not detectable in all lung cancer tissues, with slight expression in normal lung tissues." (PMID 27602961, 2016). "To determine whether the observed combined inhibitory effect of IL-24 and HMGA1 siRNA on HMGA1 signaling was restricted to one cell line, we performed experiments in an additional HCC827 lung cancer cell line." (PMID 27602961, 2016). "In conclusion we have demonstrated that IL-24 exerts its anti-metastatic activity by disrupting the SDF-1/CXCR4 axis and that IL-24-based therapy in conjunction with CXCR4 inhibitors will be more effective in attenuating lung cancer metastasis." (PMID 25775124, 2015). "We showed that the IL-24-mediated inhibitory activity on CXCR4 was comparable when IL-24 was stably induced or expressed transiently in the cancer cell lines and was independent of the lung cancer cell line used." (PMID 25775124, 2015). "In the present study we investigated whether interleukin (IL)-24 can inhibit the SDF-1/CXCR4 axis and suppress lung cancer cell migration and invasion in vitro." (PMID 25775124, 2015). "To assess IL-24 and HMGA1 protein expression in normal lung and lung tumor tissues, we performed immunohistochemistry (IHC) in a commercially available tissue microarray (TMA; BC041115b; US Biomax, Inc.), consisting of paired samples of lung cancer tissues and corresponding normal tissues." (PMID 27602961, 2016). "However, all lung cancer cell lines tested was negative for endogenous IL-24 expression, which is consistent with our TMA staining results from human lung tumors." (PMID 27602961, 2016). "Apart from measuring the IL-24 inhibitory effect on cell migration and invasion, we also investigated whether the AKT/mTOR signaling pathway that is downstream of SDF-1/CXCR4 axis and essential for lung cancer progression and metastasis was also affected." (PMID 25775124, 2015). "Also, transduction of lung cancer cells with Ad-IL-24 increased expression of ER stress-related proteins such as BiP/Grp78, GADD34, XBP-1 and transfection of cancer cells with ER-targeted IL-24 plasmids elicited increased apoptosis compared to proteins targeted to the nucleus or membrane." (PMID 18074024, 2007).
inflammatory bowel disease (23 papers, 2016 to 2025). A spectrum of small and large bowel inflammatory diseases of unknown etiology. "Furthermore, levels of IL-19, IL-20, IL-24 and IL-26 are also elevated in serum of patients with inflammatory bowel disease, which is associated with the intergenic 6q23 variants tagged by rs6920220." (PMID 27799070, 2016). "The primary objective of this study was to investigate any changes in IL-19 and IL-24 expression between inflammatory bowel disease (IBD) patients and healthy controls, as well as before and after the initiation of biologics." (PMID 39007024, 2024). "IL-24 aggravates inflammation in RA and PsO, yet it plays a protective role in inflammatory bowel disease by sustaining epithelial and mucosal integrity, thus displaying a bidirectional regulatory capacity in inflammation." (PMID 39104791, 2024). "In patients with inflammatory bowel disease, IL-24 is capable of inducing the expression of proinflammatory cytokines such as TNF-α and IL-6 as well as induction of inflammation and immune cell infiltration during tissue damage." (PMID 36806964, 2023). "Recently, a series of studies have reported the connection between IL-24 and immune inflammatory diseases, including asthma, psoriasis, systemic lupus erythematosus, atopic dermatitis, inflammatory bowel disease, and rheumatoid arthritis." (PMID 36100847, 2022). "Recently, increased interleukin (IL)-24 expression has been demonstrated in the colon biopsies of adult patients with inflammatory bowel disease (IBD)." (PMID 34078403, 2021). "Recently, increased expression of IL-19, IL-20 and IL-24 has been demonstrated in the colonic mucosa and also in peripheral blood mononuclear cells (PBMCs) of patients with inflammatory bowel diseases (IBD)." (PMID 31973719, 2020). "However, the protective role of IL-24 has been described in animal studies of several diseases such as inflammatory bowel disease." (PMID 39364404, 2024). "Numerous investigations have delved into the involvement of IL‐24 in inflammatory bowel disease (IBD)." (PMID 40338095, 2025). "IL-24 exerts anti-inflammatory effects in a variety of autoimmune diseases, including inflammatory bowel disease (IBD) and experimental autoimmune uveitis (EAU), by activating SOCS3." (PMID 38780647, 2024). "The IL-20 cytokines IL-19, IL-20, IL-22, IL-24, and IL-26 are elevated in autoimmune/inflammatory diseases, such as in the skin of patients with psoriasis, in synovial fibroblasts, and macrophages of patients with rheumatoid arthritis and in patients with inflammatory bowel disease." (PMID 29967613, 2018). "Similarly, in inflammatory bowel disease (IBD), fibroblasts contribute to inflammation through the secretion of factors like IL-11, IL-24, and IL-13RA2." (PMID 39290699, 2024).
hepatocellular carcinoma (17 papers, 2012 to 2022). A malignant tumor that arises from hepatocytes. "IL24 overexpression inhibits colony formation and cell proliferation, and induces apoptosis and cell cycle arrest of hepatocellular carcinoma cells." (PMID 35984577, 2022). "In the first study, hTERT promoter-driven E1A-Δ24-type CRAds were armed with miR-34a and/or interleukin-24 (IL-24) and tested in hepatocellular carcinoma models." (PMID 30477117, 2018). "Wenjia Lou and colleagues, proposed to use oncolytic adenovirus co-expressing miRNA-34a and IL-24 in a hepatocellular carcinoma xenografts mouse model in order to achieve a synergistic antitumoral effect." (PMID 27187371, 2016). "Sorafenib tosylate (a potent multi kinase inhibitor and a clinically proven FDA approved drug in hepatocellular carcinoma) treatment in combination with MDA-7/IL-24 has also been reported to kill renal carcinoma cells in vivo in animal models resulting in prolonged survival." (PMID 35008495, 2021). "IL24 can protect the body via the induction of tumor cell apoptosis and inhibition of angiogenesis in cancers such as colorectal adenocarcinoma and hepatic carcinoma." (PMID 33014054, 2020). "Experiments are ongoing in our laboratory to determine whether CSP I-plus could increase other antitumor domains (e.g. interferon α, interleukin-24, tumor necrosis factor α, etc) homing to hepatocellular carcinoma cells and their biologic activity." (PMID 29075040, 2017). "Furthermore, IL-24 has been shown to inhibit hepatoma cell growth in the mouse model." (PMID 29892294, 2018). "In yet another study, treatment of hepatocellular carcinoma (HCC) cells in vitro with IFN-alpha in combination with an oncolytic adenovirus expressing IL-24 (SG600-IL-24) resulted in tumor cell apoptosis." (PMID 24377906, 2013). "Similar complete elimination of xenograft hepatoma was obtained by the use of IL-24 only in the construction of Ad•AFP•E1A•ΔE1B•IL-24 (data not shown because that this paper is still under review)." (PMID 23675261, 2012).
colorectal cancer (13 papers, 2012 to 2025). A primary or metastatic malignant neoplasm that affects the colon or rectum. "Lower levels of IL24 in colorectal cancer tissues from patients are associated with lower survival rates, and colorectal carcinoma cells are sensitive to ectopic expression of IL24." (PMID 38414326, 2024). "Similarly, colorectal cancer tissue revealed significantly lower IL-24 level, which was associated with 5-year survival rate." (PMID 31921658, 2019). "assessed the anti‐tumor efficacy of an IL‐24 delivered using vaccinia virus (Guang9 strain harboring IL‐24; VG9‐IL‐24) and showed dose‐dependent cytotoxicity in colorectal cancer cell lines." (PMID 40338095, 2025). "LINC00511 was also reported to play an oncogenic role via upregulating and downregulating nuclear factor I/A (NFIA) and interleukin 24 (IL-24), respectively, in colorectal cancer." (PMID 34298879, 2021). "Interleukin (IL)-24 plays a potential anti-tumor activity in colorectal cancer in a dose-dependent manner." (PMID 31921658, 2019). "The effectiveness of MDA-7/IL-24/TRAIL therapy has been reported in models of colorectal cancer, where co-administration of oncolytic adenovirus encoding MDA-7/IL-24 and TRAIL eradicated tumors in mice." (PMID 22808125, 2012). "However, few studies focused on the regulatory activity of IL-24 to immune cell function in colorectal cancers." (PMID 31921658, 2019). "IL-24 treatment is known to induce the expression of various members of the extrinsic apoptotic pathway, such as Fas cell surface receptor (Fas), Fas ligand (FasL), Fas-associated death domain (FADD) in human ovarian cancer cells, and death receptor 4 (DR4), in colorectal cancer cell lines." (PMID 30424508, 2018). "A high concentration of IL-24 could also downregulate the Treg percentage (i.e., FoxP3 mRNA) and promote CD4+ T cell proliferation in colorectal cancer." (PMID 35752792, 2022). "However, the immunoregulatory role of IL-24 to peripheral and tumor-infiltrating T cell function in colorectal cancer was not fully elucidated." (PMID 31921658, 2019). "Downregulation of KRAS enhanced the ability of ectopic IL24 to suppress proliferation and induce apoptosis in mutant KRAS colorectal cancer cells but not in wild‐type KRAS cells." (PMID 38414326, 2024).
glioma (13 papers, 2007 to 2025). A benign or malignant brain and spinal cord tumor that arises from glial cells (astrocytes, oligodendrocytes, ependymal cells). "Taken together these results demonstrate that the optimized variant, SM7L, expands the functionality of wild-type MDA-7/IL-24 by incorporating diagnostic tracking properties, promoting greater extracellular secretion, and increasing anti-glioma activity." (PMID 22808125, 2012). "They utilized IL‐24 overexpressing UC‐MSCs (IL‐24‐UC‐MSCs), which reduced tumor cell proliferation by increasing apoptosis in U251 glioma models in vitro." (PMID 40338095, 2025). "In a xenograft model of glioma, systemic administration of MCSs loaded with Ad5F35 carrying IL-24 and/or endostatin and regulated by a Tet-on system (Ad5F35-Tet-on-E1B-Pro-Δ24-IL-24/endostatin) showed promise for glioma treatment while sparing normal cells." (PMID 38528632, 2024). "In this study, we investigated the factors affecting cell survival and apoptosis and autophagy mechanisms that destroy glioma cells by Ad/IL-24." (PMID 37280571, 2023). "Treatment of glioma cells with glutathione-S-transferase (GST)-IL24 fusion protein resulted in simultaneous activation of both autophagy and apoptosis." (PMID 24377906, 2013). "Similarly, tail vein injection of IL‐24‐UC‐MSCs resulted in suppression of tumor growth in glioma xenograft models compared with control groups." (PMID 40338095, 2025). "Furthermore, hUC-MSC were investigated as a vehicle for delivering IL-24 in the treatment of glioma." (PMID 35955703, 2022). "In addition, interleukin-24 (IL-24) in glioma cells affects the sensitivity of gliomas to cisplatin by regulating the expression levels of P-gp and Bcl-2." (PMID 35674307, 2022). "The hUC-MSC expressing IL-24 induced apoptosis and reduced tumor growth of gliomas in vivo." (PMID 35955703, 2022). "IL-24 may be a biomarker predicting the sensitivity of gliomas to chemotherapy." (PMID 35674307, 2022). "Ad-IL24 when combined with OSU-03012, an autophagy inducing drug, enhanced the antitumor activity in glioma cells by increasing ER stress and simultaneously reducing anti-apoptotic (MCL-1 and BCL-XL) protein expression." (PMID 24377906, 2013).
pancreatic cancer (13 papers, 2007 to 2025). "In another study, synergistic activity between geldanamycin (GA), an Hsp90 inhibitor, and IL‐24 was shown in pancreatic cancer cells, although the underlying mechanism contributing to this effect remains unclear." (PMID 40338095, 2025). "Similar results were also documented in pancreatic cancer, where the addition of exogenous IL‐24 activated STAT3, contributing to tumor cell death." (PMID 40338095, 2025). "MDA-7/IL-24 has the unique ability to efficiently kill almost all types of cancer cells, but pancreatic cancer cells having K-Ras mutations, show an inherent resistance to MDA-7/IL-24 treatment." (PMID 35008495, 2021). "IL24 and its receptors regulate the growth and migration of pancreatic cancer cells, which is the potential biomarkers for IL24 molecular therapy." (PMID 34852762, 2021). "The concept of “bystander” antitumor effect of MDA-7/IL-24 was first observed in pancreatic carcinoma cells and later shown to be the result of an autocrine/paracrine loop." (PMID 35008495, 2021). "It is also reported that IL-24 plays a critical antitumor role in oral, rectal and pancreatic cancers." (PMID 26528857, 2015). "Negative regulation of β-catenin and phosphatidylinositol 3-kinase (PI3K) pathways is another mechanism by which IL-24 exerts its anticancer activity in human breast, lung and pancreatic cancer cells." (PMID 24377906, 2013). "Concurring with our study results were the reports from other laboratories demonstrating IL-24 exhibited antimetastatic activity in pancreatic cancer cells." (PMID 24377906, 2013). "Thus, ROS inducers lead to the translation of IL-24 primarily on keratinocytes during inflammation and in pancreatic cancer cells, and reverse IL-24 induces ROS production in cancer cells." (PMID 37444474, 2023). "Interestingly, ROS inducers lead to the translation of IL-24 protein, resulting in toxicity in pancreatic cancer cells." (PMID 37444474, 2023). "Although, mda-7/IL-24 mRNA is actively expressed in a wide array of human cancers when infected with a replication incompetent Ad expressing mda-7/IL-24 (Ad.mda-7), pancreatic cancer cells display a unique resistance phenotype involving the inability to translate mda-7/IL-24 mRNA into protein." (PMID 35008495, 2021). "Another source of recombinant IL-24, a GST-fusion protein expressed in and purified from E.coli bacteria, has been reported to kill prostate, breast and pancreatic carcinoma cell lines, whereas others found no such attributes of GST-IL-24." (PMID 18074024, 2007).
Autoimmunity (12 papers, 2016 to 2026). The occurrence of an immune reaction against the organism's own cells or tissues. "IL-24 is also implicated in autoimmunity, where it helps regulate pathogenic T helper type 17 (Th17) responses that may aid in resolving tissue inflammation." (PMID 41301428, 2025). "Additional studies should also evaluate the safety profile of IL-24 as an adjuvant, particularly in terms of potential immune overactivation and autoimmunity." (PMID 40732170, 2025). "Understanding the intricate interplay of cytokines, such as IL-19, IL-20, and IL-24, with their receptors and their influence on autoimmunity can offer valuable insights into the therapeutic potential of Tai Chi exercise." (PMID 41551693, 2025). "IL-24 was demonstrated to act differently in different types of autoimmune diseases, and dysregulation of its expression was related with autoimmunity." (PMID 39007024, 2024). "Collectively, the current data suggest that IL-24 displays both pro- and anti-inflammatory properties depending on the type of autoimmunity and the site of inflammation." (PMID 35054813, 2022). "The tolerogenic properties of IL-24 were reported in various animal models of autoimmune diseases, suggesting the complex functions of IL-24 in regulating autoimmunity." (PMID 35054813, 2022). "Here we review IL-24’s role in autoimmunity, infectious disease response, wound repair, and vascular disease." (PMID 27271601, 2016). "Also, one of the proteins with the greatest fold increase, IL-24, is known for its tolerogenic properties in autoimmunity." (PMID 41301428, 2025). "Further studies will have to test whether IL-24 can be exploited to control Th17-driven immunopathology in autoimmunity and perhaps cancer development induced by chronic inflammation." (PMID 35819408, 2022). "The detection in these patients of IgE autoantibodies against various antigens, such as tissue factor or interleukin (IL)-24, staphylococcal exotoxins, double-stranded DNA, thyroglobulin, and thyroperoxidase, indicates a possible type I autoallergy or autoimmunity." (PMID 35744079, 2022). "Type I autoimmunity involves autoreactive IgE antibodies targeting self-antigens such as thyroid peroxidase (TPO), interleukin-24 (IL-24), thyroglobulin, and tissue transglutaminase, leading to mast cell and basophil degranulation via classical IgE–FcεRI signaling pathway." (PMID 41608596, 2026).